SOS1 (SOS Ras/Rac guanine nucleotide exchange factor 1)
Diseases named in the same sentence as SOS1 in open-access papers (continued):
Sharing a sentence is not in itself a finding about the gene and the disease.
cancer (continued). "In contrast, mutations in three other genes of the KRAS pathway, BRAF, SOS1, and NF1, were significantly more common in CDX2-suppressed cancers." (PMID 39452477, 2024). "Recently, targeting SOS1 has garnered increasing attention as a promising strategy for treating RAS-driven cancers." (PMID 38665844, 2024). "Through competitively interacting with miR-217, circ_0042881 can control the expression of SOS1, causing covert into GDP-bound state and activating downstream signal transduction cascades that contribute to the occurrence and development of cancer." (PMID 37626035, 2023). "As model system, we chose the SOS1 αH helix/KRAS complex because of the intrinsic relevance of the KRAS GTPase in cancer as well as because there are clear precedents of short peptides derived from the αH helix that selectively bind to KRAS21,22." (PMID 36697641, 2022). "In our previous research, SOS1 was a target of miR-181a-5p, a prognostic predictor in cancer, indicating that SOS1 was an oncogene in CML." (PMID 34938856, 2021). "Inhibition of the KRAS activator SOS Ras/Rac guanine nucleotide exchange factor 1 (SOS1) is an effective approach when treating cancers driven by KRAS." (PMID 33801965, 2021). "SHP2 and SOS1 are common proximal RTK signaling intermediates; the development of potent, specific inhibitors for both SHP2 (SHP099; RMC-4550) and SOS1 (BAY-293; BI-3406) has led to new approaches to treating RAS-mutated cancers." (PMID 33924994, 2021). "Due to its central function in cancer progression, many studies have found that the downregulation of SOS1 expression blocks many aspects that define cancer." (PMID 32353968, 2020). "Of the remaining 17 variants, all but three are accounted for by six genes (BRAF, CBL, MAP2K1, MAP2K2, RAF1, and SOS1) encoding members of the RAS-MAPK pathway, among which nine variants have previously been reported in either congenital disorders or cancer." (PMID 30355600, 2018). "Recently, EGFR has been reported to use SOS1 to drive constitutive activation of Nuclear Factor κB (NFκB) in cancer cells." (PMID 25980493, 2015). "Targeting SOS1 has emerged as a promising strategy for the treatment of KRAS-mutant cancers." (PMID 39437162, 2025). "In addition, we reported that RUNX1 regulates ErbB2/HER2 signaling pathway in HER2‐positive gastric cancer cells through transactivating SOS1 expression, rendering itself an ideal target for antitumor strategy toward this cancer." (PMID 40171874, 2025). "The effects of partial or complete degradation of mutated KRAS or SOS1 in cancer cells and bystander normal tissues are not clear." (PMID 39055890, 2024). "Development of inhibitors targeting SOS1 as potential therapeutic agents in cancer research." (PMID 38622665, 2024). "BET degraders in the form of proteolysis-targeting chimeras (PROTACs) combined with BAY-293-mediated SOS1 inhibition revealed marked cytotoxic synergy against mutant KRAS cancer cells and may constitute a promising option for clinical treatment." (PMID 38023987, 2023). "In addition, we have also been able to document here the unique dependence on SOS1 of human KRAS-driven LUAD by means of in silico analyses of publicly available datasets for human LUAD cancer cell lines and patients." (PMID 37730692, 2023). "SOS-1 is a GEF that binds to GDP-bound RAS proteins and is critical for tumorigenesis; in fact, the absence of SOS-1 has been to shown to have a deleterious effect on cancer cells containing KRAS mutations." (PMID 37790760, 2023). "As a result, one of the strategies to treat KRAS-mutated cancers has been the investigation of SOS1 inhibitors, which target the KRAS–SOS1 interface and do not depend on specific KRAS mutations for their action." (PMID 37894382, 2023). "In this context, decreasing the production of F-1,6-BP could attenuate SOS1/RAS binding, and thus slowdown the development of cancers driven by RAS proto-oncogene or RAS mutations (this later form being highly drug resistant)." (PMID 35626081, 2022).
cancer (continued). "Initial studies of SOS1 inhibitor BI-3406 suggest that it may benefit as many as 80%-90% of RAS-driven cancers." (PMID 35582302, 2021). "The contributions of WT RAS to proliferation and transformation in RAS-mutated cancer cells places renewed interest in upstream signaling molecules, including the phosphatase/adaptor SHP2 and the RasGEFs SOS1 and SOS2, as potential therapeutic targets in RAS-mutated cancers." (PMID 33924994, 2021). "Hence, the anti-cancer strategies targeting Grb2 is also focused on the disruption of the Grb2-Sos1 complex by blocking the interaction of Grb2 SH3 domain with Sos1." (PMID 24775912, 2014). "Targeting KRAS-driven cancers may be achieved by interfering with the activation of KRAS by SOS1." (PMID 40244134, 2025). "Therefore, KRAS A146-driven cancers may be sensitive to Son of Sevenless protein 1 (SOS1) inhibitors, combined with a MEK-inhibitor, or with SHP2, thus reinforcing the role of MEK inhibition in these tumours even in the current drug development scenario." (PMID 38261067, 2024). "SOS1, RASA1, and NF1 mutations were also significantly more often observed in CDX2-suppressed cancers (10.8%, 9.2% and 13.8%, respectively) than in non CDX2-suppressed cancers (1.8%, 1.8%, and 0.9%, Fisher’s exact test p = 0.003, 0.009, and 0.0001, respectively)." (PMID 39452477, 2024). "In addition, inhibiting SOS1 increases the sensitivity of KRAS mutant cancers to MEK inhibition." (PMID 33801965, 2021). "SOS1 could act as an oncogene and play an important role in cancers." (PMID 32609259, 2020). "A previous study has reported that concurrent inhibition of SOS1 and KRAS synergistically suppresses the proliferation of KRAS-mutant cancer cells." (PMID 39437162, 2025). "Compared with the small-molecule SOS1 inhibitor BI-3406, SIAIS562055 led to more sustained and potent suppression of downstream signaling in KRAS-mutant cancers." (PMID 39437162, 2025). "By binding to the catalytic domain of SOS1, BI-346 blocks its interaction with KRAS, reducing the formation of GTP-bound RAS and cellular proliferation in various types of KRAS-driven cancers." (PMID 40362343, 2025). "Inhibiting SOS1, a KRAS activator and crucial feedback regulator, has emerged as a promising strategy for the treatment of KRAS-driven cancers." (PMID 40362343, 2025). "Among them, SIAIS562055 emerged as a potent SOS1 PROTAC, exhibiting efficacy against not only KRAS-mutant cancer but also BCR–ABL–driven CML, both in vitro and in vivo, with evidence of robust and durable SOS1 degradation and downstream signal inhibition." (PMID 39437162, 2025). "It was identified that the compound SIAIS562055 sustainably degraded SOS1 levels and inhibit downstream effectors, exhibiting potent antitumor activity in both KRAS-mutant cancers and BCR–ABL+ CML." (PMID 39437162, 2025). "Recently, BI-3406, another SOS1 inhibitor was demonstrated to be more potent and selective for inhibiting SOS1, decreasing KRAS-GTP levels and suppressing cancer cell proliferation." (PMID 38978742, 2024). "Recently, a selective SOS1 inhibitor, BI-3406, has been reported to reduce GTP-bound RAS levels and tumor growth across KRAS-driven cancer models." (PMID 38338909, 2024). "Through the elimination of the SOS1-KRAS protein-protein interaction (PPI), these agents aim to impair the downstream signaling cascades and suppress cancer cell growth in KRAS-driven cancers, for example, colon cancer (CRC)." (PMID 39055890, 2024). "Combination of SOS1 and MEK inhibitors increase T cell infiltration while blunting pro-immune myeloid cell maturation and highlights the need for combining KRAS cancer-targeted therapy with myeloid activation to enhance and prolong anti-tumor effects." (PMID 38727236, 2024). "Several PROTACs were tested, and the best ones induced SOS1 degradation in both pancreatic and lung KRAS-driven cancer cells, showing clear antiproliferative activity when compared to the SOS1 agonist itself." (PMID 36678835, 2023).
cancer (continued). "Recently, Hofmannet.al discovered that the small molecule BI-3406 binding to the catalytic domain of SOS1 can reduce the formation of GTP-loaded RAS, thereby limit the proliferation of cancer cells driven by KRAS." (PMID 36713456, 2022). "Other biomarkers include Son of sevenless homolog 1 (SOS1) that is stimulated by ERK signaling activation, especially in higher stages of cancer." (PMID 36140796, 2022). "Inhibition of SOS1 can increase the chemosensitivity of KRAS-amplified cancer cells to MEK inhibition and the SOS1 inhibitor BI-3406 has been demonstrated to synergize with the MEK inhibitor trametinib." (PMID 36048281, 2022). "BI-3406, a novel SOS1-KRAS interaction inhibitor designed to target the catalytic domain of SOS1, has been combined with trametinib and sensitized KRAS-driven cancers to MEK inhibition in mouse models." (PMID 34946644, 2021). "Another inhibitor of the SOS1-KRAS interaction is BAY-293, which has demonstrated efficacy in KRAS-driven cancers in preclinical studies." (PMID 35083149, 2021). "BI-3406 is a potent and selective SOS1:K-RAS interaction inhibitor that potently decreased the formation of GTP-bound RAS and reduced cell proliferation of RAS-driven cancers both in vitro and in vivo." (PMID 35582302, 2021). "BI-3406 is a potent and selective inhibitor of the SOS1-KRAS interaction that attenuates reactivation by MEK inhibitors and enhances the sensitivity of KRAS-dependent cancers to MEK inhibition in preclinical models." (PMID 35083149, 2021). "The cancer cells were either exposed to EGFR inhibitors only or to a combination of EGFR and SOS1 inhibitors." (PMID 32897190, 2020). "This pattern of heterogeneity was similar when considering a broader list of pan-cancer driver genes, with private amplification events seen in ERBB3, RHEB, SOS1, SOS2, and EZH2." (PMID 30348992, 2019). "In the cancer pathway cluster, CASP9 and PIK3R1 are both involved in 7 different cancer pathways, while SOS1 and TCF7L2 are both involved in 5 different pathways." (PMID 23281828, 2012). "As expected, our immunohistochemical analysis on the cancers developed on the CAM demonstrated that Chb‐M' but not Chb‐S downregulates the RUNX‐target gene product SOS1." (PMID 40171874, 2025). "Taken together, these data suggest that SIAIS562055-induced degradation of SOS1 leads to the suppression of downstream signaling, which effectively inhibits the proliferation of KRAS-mutant cancer cells and shows synergistic effects when combined with KRAS inhibitors." (PMID 39437162, 2025). "Additionally, SOS1 PROTACs based on SOS1 inhibitors or agonists have been developed, providing a new avenue for the treatment of KRAS-mutant cancers." (PMID 39437162, 2025). "Despite these promising advances, there is currently no approved SOS1 inhibitor, and most of these candidates are designed to be combined with anti-cancer drugs targeting the KRAS-MAP kinase pathway." (PMID 38665844, 2024). "Son of sevenless 1 (SOS1), a crucial node in the RAS signaling pathway, could modulate RAS activation, offering a promising therapeutic strategy for RAS-driven cancers." (PMID 38665844, 2024). "Nevertheless, there are many GEFs (including SOS2) that can replace the function of SOS1; hence, it is unclear whether inhibiting SOS1 alone is sufficient to reduce KRAS signaling in humans to prevent cancer." (PMID 36831298, 2023). "Recently, BI-3406, a SOS1–KRAS interaction inhibitor, was shown to attenuate SOS1 dependent feedback reactivation induced by MEK inhibitors and thereby enhance sensitivity of KRAS-dependent cancers to MEK inhibition." (PMID 37370689, 2023). "Importantly, the binding F-1,6-BP/SOS1 is an evolutionary conserved mechanism that links glycolysis to RAS activation in yeast, as well as in mammalian and cancer cells." (PMID 35626081, 2022).
cancer (continued). "Moreover, other genes from diverse functional groups appeared in our analysis, such as signal transducers promoting cancer growth (CD53, RAB33A, GNA11, CANX, OCRL, GIPC1, and SOS1), microtubule formation (KIF21B) and cell migration (ASAP2)." (PMID 29535628, 2018). "In fact, a small‐molecule inhibitor targeting SOS1 was shown to inhibit growth of cancer cells with wild‐type K‐Ras, but not cells with mutant K‐Ras, including A549." (PMID 28296343, 2017). "The small-molecule SOS1 inhibitor BI-3406 abolishes SOS1-KRAS interaction in vitro and in KRAS-dependent cancer models without affecting KRAS wild-type cells." (PMID 38023987, 2023). "Indeed, multiple upstream regulators of Ras activation such as SOS1, SOS2, PTPN11, and GAB1 exhibit significant negative correlations with NF1 in the Cancer Dependency Map, supporting the importance of these genes as functionally opposing NF1 function." (PMID 40587782, 2025). "It is thought that efforts to treat RAS-driven cancers with MEK inhibitors have failed in part as inhibition of MEK reduces the activity of ERK1/2, resulting in the release of a negative feedback loop, thus increasing the activity of SOS1-dependent formation of GTP-bound RAS." (PMID 35582302, 2021). "For example, the following top 100 MDS genes can be mentioned that are not yet covered by approved or experimental cancer or antineoplastic drugs [according to DrugBank, DGIdb, FDA6, HMDB, Tocris7, GeneCards databases]: GRB2, SOS1,SOS2, SHC1, GNB1, CREB1, GNG2, GNAQ, GNB5, GNAI2." (PMID 30728774, 2019).
tumor (64 papers, 2004 to 2025). "Through experiments in pancreatic cancer cell lines, it has been shown that the inactivation of SOS1 decreases the survival of RAS-mutated tumor cells." (PMID 37894382, 2023). "SOS1 inhibitors are currently being investigated in several KRAS-mutated tumor types in phase I clinical studies, both alone and in combination with other drugs." (PMID 37894382, 2023). "We found that the expression levels of Ki67, GRF2 and SOS1 were strongly and significantly associated with each other in primary tumors (n = 22) and with residual tumor size (n = 12)." (PMID 32298357, 2020). "The authors hypothesized that there could be an association between this germline mutation of the SOS1 gene and the tumor development." (PMID 39336782, 2024). "Furthermore, we also documented a specific, remarkable regression caused by SOS1 ablation on preexisting tumors of 6-month-old mice in comparison to similarly aged, tumor bearing, SOS1/2WT or SOS2KO mice." (PMID 37730692, 2023). "Moreover, down-regulation or loss of SOS1 lead to a decrease in the survival rate of tumor cells carrying KRAS mutations." (PMID 36139627, 2022). "Furthermore, SOS1 expression was found to be linked to tumor progression and metastasis in LUSC." (PMID 38622665, 2024). "In one of the studies, combining trametinib with the new SOS1-KRAS interaction inhibitor BI-3406, which targets the catalytic region of SOS1, makes KRAS-driven tumours more susceptible to MEK inhibition in mice models." (PMID 40483365, 2025). "The strategy followed for KRAS.SOS1 ternary complex can be extended to other RAS proteins involved in tumor progression, such as targeting the HRAS.SOS1 ternary complex with known 3-dimensional structure." (PMID 40244134, 2025). "Overactive SOS-1 can further enhance this pathway, leading to increased tumor growth and resistance to apoptosis." (PMID 40141222, 2025). "The results indicate that the DNMT1/miR-152-3p pathway promotes the self-renewal and tumor growth of A549-derived LCSLCs through the regulation of SOS1 expression." (PMID 38622665, 2024). "The combination of aCTLA-4-4 and aPD-1 with SOS1+MEKi was able to significantly delay tumor growth and increase survival." (PMID 38727236, 2024). "This study establishes a critical role for the complex interplay between miR-152-3p, DNMT1, and SOS1 in regulating and maintaining self-renewal and tumor growth within LCSCLs." (PMID 38622665, 2024). "This, in turn, leads to the alleviation of the inhibitory effect of miR-152-3p on the target gene SOS1, ultimately activating SOS1 and playing an essential role in self-renewal and tumor growth of LCSLC." (PMID 38622665, 2024). "The SOS1-directed PROTAC 9d contains the VUBI-1 SOS1 agonist that kills tumor cells by a downregulation of the MAPPKs in response to SOS1 overactivation." (PMID 39055890, 2024). "To delve deeper into the role of DNMT1/miR-152-3p/SOS1 expression in the self-renewal and tumor growth of NSCLCs, we conducted a comparative analysis." (PMID 38622665, 2024). "Our report confirms the possibility of DNMT1/miR-152-3p/SOS1 regulating the tumor growth and self-renewal of LCSLCs, providing new insights into the initiation and progression of NSCLC." (PMID 38622665, 2024). "Several studies have demonstrated the relationship between SOS1 and miRNAs in the context of tumor radiation resistance, prognosis, and apoptosis." (PMID 38622665, 2024). "We aimed to investigate the relationship between DNMT1, miR-152-3p, and SOS1, which collectively regulate self-renewal and tumor growth in NSCLC cells." (PMID 38622665, 2024). "Taken together, these data suggested that GTP‐loaded PPDPF enhanced the GEF activity of SOS1, which was indispensable for the tumor‐promoting function of PPDPF in PDAC." (PMID 36453576, 2023).